CXCR1 (C-X-C motif chemokine receptor 1)
Diseases named in the same sentence as CXCR1 in open-access papers (continued):
Sharing a sentence is not in itself a finding about the gene and the disease.
tumor (continued). "Analysis of pharmacodynamic markers within harvested PTEN-deficient tumour samples similarly indicated IR to induce the expression of Bcl-2, a known mediator of RT resistance in a number of cancer models, but that this was attenuated by inhibition of CXCR1/CXCR2 signalling." (PMID 32743555, 2020). "Given the limitations that our obese and non-obese patient cohorts were small, and follow-up duration relatively short, our data suggest that epithelial CXCL1 expression and CXCR1-positive tumour stroma in obese patients may be associated with more aggressive disease features." (PMID 27241286, 2016). "By simultaneously targeting the IL-8/CXCR1/2 axis, we aim to disrupt the immunosuppressive barrier and enhance the ability of ICIs to elicit a robust anti-tumor immune response." (PMID 41002568, 2025). "IL-8 is produced by tumor cells and cells in the tumor microenvironment, acting through its receptors CXCR1 and CXCR2 to stimulate cell migration, proliferation, and survival." (PMID 40725273, 2025). "G31P inhibits AKT and ERK phosphorylation by directly blocking CXCR1/2 signaling in tumor cells and indirectly decreases CXCL1/8 driven paracrine activation, consistent with evidence that CXCR1/2 blockade inhibits PI3K/AKT signaling in multiple cancers." (PMID 41425704, 2025). "These molecules, acting in a CXCR1/2-dependent manner, recruit neutrophils and polarize them into the pro-tumor N2 subtype, thereby facilitating tumor progression." (PMID 41445734, 2025). "The importance of the CXCR1/2-IL8 axis in neutrophil chemotaxis and the multiple pro-tumor functions mediated by this axis make CXCR1/2-IL8 a desirable therapeutic target." (PMID 40092983, 2025). "Particularly when combined with anti-PD-1 therapy, CXCR1/2 antagonists significantly reduced tumor burden and prolonged the survival time of the mice." (PMID 40573881, 2025). "REEP5 has been recognized as a binding partner of CXCR1, subsequently triggering the IL-8-CXCR1/2 signaling pathway and facilitating the growth and metastasis of diverse tumor cell types." (PMID 40584831, 2025). "These macrophages, characterized by high CXCR1 expression, can suppress cytotoxic T-cell proliferation and facilitate tumor progression." (PMID 40149983, 2025). "The IL-8/CXCR1/2 axis has emerged as a critical target in cancer therapy due to its multifaceted roles in tumor growth, angiogenesis, metastasis, and immune suppression (CXCR1/2 inhibitors)." (PMID 41002568, 2025). "CXCL8, a pro-inflammatory chemokine, binds CXCR1/CXCR2 receptors to drive tumor progression via TME interactions." (PMID 40596054, 2025). "Although these two subsets share certain chemokine receptors on their surface, such as CCR5 and CXCR1, they exhibit distinct chemokine response patterns and migration behaviors within the tumor microenvironment (TME)." (PMID 40141420, 2025). "For this reason, the role of CXCR1 in MM cells in tumor processes should be investigated in the future." (PMID 40940985, 2025). "The CXCL8/CXCR1/2 axis has been identified as a key signaling pathway driving neutrophil recruitment to the tumor site; once recruited, TANs are exposed to local cytokines, including TGF-β, that further reinforce their immunosuppressive characteristics." (PMID 40281554, 2025). "The tumor-produced IL-8 is a potent chemoattractant that recruits CXCR1/2-expressing human myeloid-derived suppressor cells to tumor foci, playing a crucial role in immune resistance." (PMID 40362634, 2025). "We analyzed publicly available single-cell data from HNSCC patients (GSE234933) to validate which cell types are specifically associated with the IL-8 receptors CXCR1 and CXCR2 in the tumor microenvironment of HNSCC patients." (PMID 39905539, 2025). "CXCR1/2 antagonism by G31P attenuates chemotherapy-induced pulmonary inflammation and enhances the anti-tumor efficacy of gefitinib in NSCLC." (PMID 41425704, 2025).
tumor (continued). "Significantly, during tumor development, a subset of key senescent macrophages with high C-X-C chemokine receptor type 1 (CXCR1) expression has been identified." (PMID 40149983, 2025). "In ovarian cancer models, electroporation of NK cells with CXCR1 mRNA enhanced their migration to tumor sites and improved tumor control in vivo." (PMID 41462483, 2025). "NETs induced by CXCR1/2 agonists have been shown to impede cytotoxic lymphocyte interactions with tumor cells in mouse cancer models and in vitro systems." (PMID 40986319, 2025). "CXCL8 recognizes and activates the G protein-coupled receptors (GPCRs) CXCR1/2, thereby inducing the activation and trafficking of inflammatory mediators and facilitating tumour progression, invasion, and metastasis." (PMID 39962077, 2025). "In mouse models, blocking CXCR1/2 significantly reduced the recruitment of neutrophils and myeloid-derived suppressor cells (MDSCs) to the tumor microenvironment, thereby reducing immune suppression and enhancing the anti-tumor immune response." (PMID 40573881, 2025). "Their signaling via CXCR1/2 contributes to neutrophil infiltration and paracrine signaling which sustains the inflammatory tumor microenvironment." (PMID 41425704, 2025). "This study provides evidence that the CXCR1/2 antagonist G31P enhances the anti-tumor efficacy of gefitinib and protects against chemotherapy-induced lung inflammation and fibrosis." (PMID 41425704, 2025). "CXCL8 promotes tumor cell proliferation, angiogenesis, and chemoresistance, while neutrophil infiltration mediated by CXCR1/2 correlates with poor clinical outcomes." (PMID 41425704, 2025). "They electroporated NK cells with two mRNA constructs encoding the chemokine receptor CXCR1 and a CAR construct targeting tumour-associated NKG2D ligands." (PMID 40650066, 2025). "Inhibition of CXCR1/2 signaling has been shown to synergize with PD-1/PD-L1 treatment, resulting in a reduction of mesenchymal tumor characteristics in mouse models of breast and lung cancer." (PMID 40006729, 2025). "Tumor-associated macrophages (TAMs) facilitate metastasis of PTC cells via secretion of CXCL8/interleukin (IL)-8 and paracrine interaction with CXCR1/2." (PMID 40313970, 2025). "The rationale for combining IL-8/CXCR1/2 inhibitors with ICIs stems from the ability of the IL-8/CXCR1/2 axis to create an immunosuppressive tumor microenvironment (TME)." (PMID 41002568, 2025). "In summary, the IL-8/ CXCR1 axis in FME is pivotal to tumor promotion via paracrine and autocrine signaling." (PMID 38891100, 2024). "Western blot analysis also showed the increased phosphorylated NF-κB and Vimentin expression and decreased E-cadherin expression in tumor cells co-cultured with CXCR1+ neutrophils, which reversed upon addition of reparixin." (PMID 39638994, 2024). "Modifying CAR-NKs with an NFκB-inducible IL-12 promoter (TRUCK) or expression of CXCR1 also enhances tumor homing, cytotoxicity, and monocyte recruitment by the CAR-NK." (PMID 38785789, 2024). "In ccRCC, the ELR+CXCL/CXCR1/2 axis promotes tumour cell proliferation and angiogenesis, mirroring observations of CKD with a similar endpoint of chronic inflammation and the development of cancer-associated fibroblasts." (PMID 38397987, 2024). "Inhibition of CXCR1/2 was achieved via treatment of tumor cells in culture with the small molecule inhibitor, SX-682; chemotherapy agents included the alkylating agent cisplatin and the microtubule-targeting agent, docetaxel." (PMID 39639338, 2024). "Intriguingly, the induction of NETosis by tumor‐derived chemokines depends on CXCR1/CXCR2, which regulates leukocyte trafficking toward inflammation and transduces the Gi signaling." (PMID 39015554, 2024). "Tumor lysates from MDA-PCa-2b-CXCR1 (0.618 ± 0.013) xenografts displayed a ~40% decrease in VEGF expression relative to MDA-PCa-2b-CXCR2 (0.997 ± 0.110) and MDA-PCa-2b-Vec (1.000 ± 0.074)." (PMID 39766038, 2024).
tumor (continued). "Considering the significant increase of CXCR1+ neutrophils in resistant samples, we then conducted CellChat analysis to elucidate the role of CXCR1+ neutrophils within the tumor microenvironment." (PMID 39638994, 2024). "To determine the effect of ITM2A in MDA-PCa-2b-CXCR1 tumor growth, we first attempted to generate MDA-PCa-2b cell lines deficient in ITM2A expression." (PMID 39766038, 2024). "Analysis of ligand-receptor pairs revealed interactions between CXCR1+ neutrophils and tumor cells involving TGFA-EGFR and EGF-EGFR, potentially explaining aspects of resistance to third-generation EGFR-TKIs due to sustained EGFR activation." (PMID 39638994, 2024). "In another study, NKG2D-specific CAR-NK cells modified with CXCR1 demonstrated enhanced in vitro migration into tumor supernatants and increased tumor infiltration in vivo in human subcutaneous and intraperitoneal ovarian cancer xenograft models." (PMID 38927974, 2024). "Another strategy is the generation of CAR-T cells expressing enzymes against tumor stroma (e.g., heparanase) or chemokine receptors (e.g., CXCR1 and CXCR2) matching tumor chemokines and promoting infiltration." (PMID 38201305, 2024). "Pathway enrichment analysis of differential genes showed significant upregulation of NF-κB and EMT pathways in tumor cells co-cultured with CXCR1+ neutrophils, which was notably reduced in reparixin treatment group." (PMID 39638994, 2024). "The presence of CXCR1+ neutrophils contribute to the development of resistance by interacting with tumor cells." (PMID 39638994, 2024). "Heatmap analysis of NF-κB signaling pathway-related key genes showed that tumor cells co-cultured with CXCR1+ neutrophils exhibited gene expression patterns similar to resistant group, which reverted to unprocessed upon reparixin treatment." (PMID 39638994, 2024). "Spatial analysis showed that increased CXCR1+ neutrophils predominantly infiltrated into the tumor core in resistant samples and the average distance of neutrophils to tumor cells markedly reduced from 33 to 19 μm." (PMID 39638994, 2024). "Cell communication analysis demonstrated strong communication of CXCR1+ neutrophils with various cells, particularly enhanced communication with tumor cells and Tregs after drug resistance." (PMID 39638994, 2024). "Spatial analysis further showed that the average distance of CXCR1+ neutrophils to tumor cells markedly reduced from 33 to 19 μm and increased CXCR1+ neutrophils predominantly infiltrated into the tumor core in resistant samples." (PMID 39638994, 2024). "Increased CXCR1 expression in stage 4 entails disease aggressiveness, as CXCR1 plays a crucial role in tumour cell migration and invasion." (PMID 38426619, 2024). "CXCR1/2 regulation of tumor immune microenvironment can suppress T cell responses in as-yet-unappreciated manners." (PMID 38786066, 2024). "The interplay between UPP1high tumor cells and SPP1+ macrophages was linked with a variety of chemokines, including CCL2_CCR2, CCL3_CCR5, CXCL3_CXCR2, and CXCL8_CXCR1, as well as interactions such as IL1B_IL1_receptor and TGFB1_TGFbeta_receptor1." (PMID 38331898, 2024). "CXCR1, in association with its ligand IL8, governs leukocyte recruitment into tumor cells and influences the tumor immune response." (PMID 38388460, 2024). "Deep analysis of scRNA and bulk RNA sequencing data revealed the increased interactions between CXCR1+ neutrophils and tumor cells and activated TNF-α/NF-κB signaling pathway in tumor cells of resistant samples." (PMID 39638994, 2024). "It primarily binds to CXCR1 and CXCR2 receptors expressed on monocytes, granulocytes, endothelial cells and tumor-associated macrophages, leading to neutrophil recruitment at sites of inflammation." (PMID 38233759, 2024). "The average distance of CXCR1+ neutrophils to tumor cells significantly decreased from 33 μm in pretreatment samples to 19 μm in resistant samples." (PMID 39638994, 2024).
tumor (continued). "Overall, the signalling induced by IL-8 on either CXCR1 or CXCR2 influences many aspects of tumour progression within the TME, providing promising targets for therapeutic interventions." (PMID 39199570, 2024). "The live imaging techniques were employed to monitor the dynamics of CXCR1+ neutrophils within the live tumors, revealing substantial infiltration through tumor vasculature, which was effectively reduced by reparixin." (PMID 39638994, 2024). "In pancreatic cancer, inhibiting CXCR1/2 with SC-479833 demonstrated anti-tumour and anti-metastatic effects, along with decreased neutrophil recruitment." (PMID 39199570, 2024). "For instance, it has been showed that CAR-T cells overexpressing the IL-8 receptors CXCR1 or CXCR2 had better tumor infiltration and anti-tumor effects." (PMID 38622705, 2024). "Recent studies have demonstrated that IL-8/CXCR1 signaling contributes to the progression of PADC by promoting tumor cell survival, invasion, and resistance to apoptosis." (PMID 38891100, 2024). "In a stage‐wise analysis based on the American Joint Committee on Cancer (AJCC) classification (stage 3 and stage 4), all genes were upregulated in stage 3 cancers, except CXCR1, which showed higher expression in stage 4 tumours." (PMID 38426619, 2024). "Studies have demonstrated that matching CAR-NK cells with tumor-secreted chemokines (such as IL-8 and receptor CXCR1) enhances tumor migration and invasion." (PMID 38245520, 2024). "Culture supernatant from tumor cell lines also induced NETosis in CXCR1 and CXCR2 signaling-dependent manners." (PMID 38786066, 2024). "In vitro and in vivo experiments validated that CXCR1+ neutrophils resulted in resistance to third-generation EGFR-TKI via activating TNF-α/NF-κB signaling pathway in tumor cells." (PMID 39638994, 2024). "The IL-8/CXCR1 signaling pathway exemplifies this theory, as it not only enhances the intrinsic aggressiveness of tumor cells but also conditions the microenvironment to support their growth and survival." (PMID 38891100, 2024). "CAR-T cells expressing CXCR2 appeared more efficacious at tumor homing than CXCR1-expressing CAR-T cells, while also decreasing the tumor burden and increasing T-cell infiltration relative to CAR-T cells not expressing CXCR2." (PMID 38339310, 2024). "The tumor-suppressive effect of CXCR1 is unclear but seems to correlate with an increase expression of the tumor suppressor ITM2A." (PMID 39766038, 2024). "Low levels of CXCR1 and CXCR3 are associated with a decreased tumor volume, decreased alpha fetoprotein levels, and a decreased TNM tumor stage 110." (PMID 38481800, 2024). "It has been shown that pharmacological inhibition of CXCR1 or CXCR2 leads to the promotion of the antitumor T cell response as a consequence of the limited neutrophil tumor infiltration." (PMID 38398111, 2024). "enhanced the response of CAR-NK cells to tumor-secreted chemokines (IL-8 receptor CXCR1) by matching CAR-NK cells Inhibition of tumor migration and invasion." (PMID 38245520, 2024). "Endothelial cells physiologically express CXCR1/2, the stimulation of which activates pro-tumour angiogenesis, a key phenomenon in the development of ccRCC." (PMID 38397987, 2024). "Agreeing with this study, we also see high expression of CXCL1 in tumor cells, and high expression of the corresponding receptor CXCR1 in neutrophils, suggesting a mechanism by which neutrophils are recruited into the interior of the tumor." (PMID 38712065, 2024). "Typically, in the case of the tumor microenvironment, inflammatory pathways can be utilized by the tumor to aid in tumor progression; one such pathway is the CXCR1/2 pathway." (PMID 36831112, 2023). "CXCL8, the key ligand of CXCR1/2, is overexpressed in various solid tumors and has been shown to promote tumor development." (PMID 37540227, 2023).
tumor (continued). "Cellular responses, such as tumour cell survival and proliferation, are the consequences of CXCR1 and CXCR2 mediated activation of (PI3K)/Akt and MAPK signalling pathways." (PMID 37170733, 2023). "CXCL3 acts on the CXCR2 receptor, whereas CXCL6 acts on both CXCR1 and CXCR2 receptors, ultimately resulting in the recruitment of tumor-associated neutrophils and the promotion of tumor angiogenesis." (PMID 37161430, 2023). "The CXCR1-engineered NK cells showed enhanced in vitro migration toward tumor supernatants and increased in vivo infiltration into human tumors in subcutaneous and intraperitoneal xenograft models." (PMID 36717905, 2023). "As inflammatory immune cells, neutrophils alter the tumor microenvironment by expressing chemokine receptors CXCR1 and CXCR2." (PMID 37480143, 2023). "We previously demonstrated that targeted deletion of Cxcr2 in myeloid cells or systemic treatment with the CXCR1/CXCR2 antagonist SX-682 conferred anti-tumor immunity via reduction of MDSC infiltration into the TME and enhanced CD8 + T cell activation." (PMID 37270599, 2023). "CXCR1/CXCR2 ligands, including CXCL1-3, 5–8 are produced by endothelial cells, tumor-associated macrophages, cancer-associated fibroblasts, adipocytes, and cancer cells." (PMID 37270599, 2023). "We extracted the expression data of CXCR members (CXCR1/2/3/4/5/6) from TCGA in each sample and calculated the expression differences between normal and tumor samples in each tumor for different subtypes of CXCR members." (PMID 37626511, 2023). "In pathologic tumor conditions, the CXCR1 axis elicits a response that promotes metastasis/migration, invasion, neovascularization, increased proliferation, and chemotherapy resistance." (PMID 36831112, 2023). "Another study investigated the transfection of NK cells with chemokine receptor CXCR1-mRNA construct and a CAR-mRNA construct against tumor-associated NKG2D ligands." (PMID 36717905, 2023). "When delivered intravenously, CXCR1/2 modified CD70-CAR T-cells showed more remarkable CAR T-cell migration to the tumor site than their CD70-CAR T-cell-treated counterparts." (PMID 38136398, 2023). "The percentage of elevated concentrations of CXCL1 and CXCR1 was higher than that of the classical tumor biomarker and increased in the combined measurement of these proteins with CEA." (PMID 37509572, 2023). "Stromal-specific knockout (cKO) of Yap1 in murine models shaped the GROα-enriched microenvironment, facilitating in vivo tumor colonization, but this effect was reversed after Cxcr1/2 depletion in OvCa cells." (PMID 36624516, 2023). "Serum concentrations of CXCL1, CXCR1, and the classical tumor marker (CEA) were measured using immunoenzyme assays, while CRP levels were assessed with the immunoturbidimetric method." (PMID 37509572, 2023). "For example, when binding to CXCR1, it mainly promotes tumor cell proliferation and can promote angiogenic in tumor tissues." (PMID 37954103, 2023). "These CXCR1 and CXCR2 ligands play a significant role in the recruitment of neutrophils and myeloid-derived suppressor cells (MDSCs) to the tumor microenvironment (TME), both of which are associated with poor outcomes." (PMID 37270599, 2023). "Increased tumor angiogenesis and shorter median OS of LC are associated with the expression of IL8 mRNA, which is known to act through CXCR1/2, in the lung TME induced by infiltrating macrophages via the NFKB pathways." (PMID 37770496, 2023). "CXCL8 through CXCR1 can also increase the count of Treg cells in the tumor microenvironment by increasing the expression of TGF-β." (PMID 37686093, 2023). "Neutrophils are attracted to the tumor microenvironment through chemokine receptors, CXCR1 and CXCR2, which are expressed at high levels on the surface of neutrophils." (PMID 37869087, 2023). "We also investigated the effect of adding SX682, a small-molecule inhibitor of CXCR1/2 known to reduce MDSC trafficking to tumor microenvironment, to our therapeutic approach." (PMID 37190294, 2023).